CRP (C-reactive protein)
Diseases named in the same sentence as CRP in open-access papers (continued):
Sharing a sentence is not in itself a finding about the gene and the disease.
Insulin resistance (continued). "High levels of inflammatory mediators, such as tumor necrosis factor alpha (TNF-α), interleukin 6 (IL-6), and C-reactive protein (CRP), might contribute to an increase in insulin resistance." (PMID 28403353, 2017). "Greater TNFα and CRP levels in the CM group could contribute to the study findings because both TNFα and CRP have been indicated to promote insulin resistance." (PMID 28713332, 2017). "Circulating very-long-chain SFAs (C20:0, C22:0 and C24:0) had mixed associations with different metabolic markers, including a positive association with LDL-C, an inverse association with triglycerides (TG) and an inverse association (C24:0 only) with C-reactive protein (CRP) and insulin resistance." (PMID 29145892, 2017). "Our clinical studies showed that the A-FABP concentration is associated with the body mass index; concentrations of triglycerides, high-density lipoprotein cholesterol, adiponectin, and C-reactive protein; and the homeostasis model assessment–insulin resistance value." (PMID 29017449, 2017). "The results suggest that activation of GalR1 in brain may inhibit CRP secretion to ameliorate insulin resistance." (PMID 27127795, 2016). "Recent attention has been directed towards the divergent results of vitamin D between prospective studies and randomized trials; indeed, this systematic review also shows inconsistencies for markers of inflammation (i.e. CRP, IL-6), glucose measures and insulin resistance (i.e. HbA1c, HOMA-IR)." (PMID 27116227, 2016). "A study demonstrating the anti-inflammatory properties of n-3 PUFA via suppression of toll-like receptor 4 (TLR4) activation in muscle reported improvements in inflammatory markers (TNFα, CRP, IL-6) and insulin resistance as measured from oral glucose and insulin tolerance tests (OGTT and ITT)." (PMID 27258299, 2016). "The results of another study indicate that elevated serum ferritin levels (without evident Fe overload) may affect glucose homeostasis, leading to insulin resistance in conjunction with inflammatory changes (seen as elevated C-reactive protein levels)." (PMID 27071614, 2016). "After adjustment for age, waist circumference, resistin, CRP, PAI-1, adiponectin and glycated hemoglobin levels, the association of having insulin resistance and higher levels of IL-6 (OR = 1.390, p = 0.005) and MCP-1 (OR = 1.006, p = 0.026) became stronger (model 4)." (PMID 26862350, 2016). "Our current results indicated that the CRP levels were markedly decreased by central administration of M617, suggesting that activation of GalR1 in brain might reduce CRP discharge to ameliorate insulin resistance." (PMID 27127795, 2016). "Angiotensin II promotes the growth and differentiation of adipocytes, the decrease in plasma adiponectin levels and increase of insulin resistance, induces the expression of C-reactive protein, and results in the secretion of leptin, which in turn activates the renal sympathetic nerve." (PMID 26911143, 2016). "Elevated C-reactive protein (CRP) levels are also related to insulin resistance." (PMID 27115749, 2016). "Forty-six overweight/obese (BMI ≥25 kg/m2) African American and Caucasian women 19–35 years were classified by cardiometabolic risk factors, including elevated blood pressure, triglyceride, glucose and C-reactive protein, low high density lipoprotein, and insulin resistance (MUO ≥2; MHO, <2)." (PMID 26383251, 2015).
Insulin resistance (continued). "Despite diagnosis of normal glucose tolerance, pGDM are characterized by hyperglycemia and insulin resistance compared to healthy controls, accompanied by decreased adiponectin and increased CRP concentrations, thus linking metabolic disturbances to an increased cardiovascular risk in pGDM." (PMID 25873951, 2015). "Similar to the evidence from rodent studies, we found that longer nighttime fasting intervals were associated with significantly lower concentrations of CRP and non-significantly lower concentrations of insulin resistance biomarkers." (PMID 26305095, 2015). "Although it is known that TNF-α stimulates the synthesis of CRP in the liver, correlation coefficient between circulating levels of TNF-α and CRP is 0.173 in the present study and 0.27 in a large, multiethnic population of the Insulin Resistance Atherosclerosis Study." (PMID 25105150, 2014). "Method comparisons were based on results from a simulation study, and also the estimation of the association between abdominal adiposity and two biomarkers; C-Reactive Protein (CRP) (inflammation marker,) and Insulin Resistance (HOMA-IR) (marker of insulin resistance)." (PMID 24681553, 2014). "T2DM is found to display increased concentrations of C-reactive protein (CRP) and pro-inflammatory cytokines, such as tumor necrosis factor-α (TNF-α) and interleukins 1 and 6 (IL-1, IL-6), which are implicated in instigating metabolic insulin resistance." (PMID 24650557, 2014). "In addition, the fractalkine-MetS association was evaluated to determine any potential dependence upon well-established risk factors of MetS, such as central obesity, C-reactive protein (CRP), insulin resistance, and dyslipidemia." (PMID 24883062, 2014). "Evaluation was made both using simulations and by applying the methods to a large data set to estimate well-known associations of abdominal adiposity (waist circumference, WC) on inflammation (measured using C-reactive protein, CRP) and insulin resistance (measured using HOMA-IR), respectively." (PMID 24681553, 2014). "High-sensitivity C-reactive protein (hs-CRP) level is often higher in hyperuricemic patients than in the general population, hs-CRP level was found to be an independent predictor of homeostatic model assessment with insulin resistance." (PMID 25400699, 2014). "Thus, the observed association between fractalkine concentrations and development of MetS cannot be attributed mainly to central obesity, CRP, insulin resistance, or dyslipidemia." (PMID 24883062, 2014). "CRP may also inhibit the expression of peroxisome proliferator-activated receptors and precede insulin resistance." (PMID 25105149, 2014). "C-reactive protein (CRP) is an acute-phase protein secreted by the liver and it is used as a marker for subclinical inflammation and CVD risk but the link between CRP and insulin resistance remains unclear." (PMID 23537367, 2013). "In addition, C-reactive protein are shown to induce hepatic insulin-resistance which leads to poor liver regeneration." (PMID 24141186, 2013). "In addition, the serum C-reactive protein (CRP), widely used as an indicator of systemic inflammation is associated with insulin resistance and the risk of MetS development." (PMID 24719625, 2013). "However, higher insulin levels and a greater degree of insulin resistance were noted among PsA patients, and these remained significant even after controlling for BMI and CRP." (PMID 23843781, 2013). "Moreover, SAD explained a greater portion of variation of insulin resistance and CRP levels in immigrant women from the Middle East and native Swedish women, and Chinese hypertensive patients." (PMID 24167560, 2013). "Multiple linear regression analysis was used to assess the association of television screen time and computer/reading time with cardio-metabolic biomarkers [blood pressure, lipids, glucose, adiponectin, C reactive protein and homeostasis model assessment of insulin resistance (HOMA-IR)]." (PMID 23718927, 2013).
Insulin resistance (continued). "CRP plays a role in inflammation and insulin resistance and may be derived from adipose tissue or elevated as a consequence of higher IL-6 and MCP-1 levels." (PMID 24227909, 2013). "Also, leptin is also reported to be related to insulin resistance and high C-reactive protein levels, both of which have been shown to be related to CKD." (PMID 22666590, 2012). "In 520 Chinese patients with type 2 diabetes, insulin resistance was associated with CRP levels independent of abdominal obesity." (PMID 21663637, 2011). "They had a lower mean ponderal index and waist circumference, but their mean sum of skinfolds, fat mass index, HbA1c, fasting glucose, fasting insulin, HOMA insulin resistance, C-reactive protein and triglyceride were higher, while HDL-cholesterol levels were lower." (PMID 20421924, 2010). "Models were also computed including HOMA insulin resistance, but although this was associated significantly with CRP, its inclusion did not change the results appreciably." (PMID 21078191, 2010). "CRP is related to insulin resistance and is a marker of endothelial dysfunction." (PMID 20847810, 2010). "Conversely, genetic variants associated with C-reactive protein (CRP) level have not been found to predict insulin resistance or coronary heart disease, casting doubt on the causal role of CRP with respect to these conditions." (PMID 21048988, 2010). "Increases in spleen size and CRP levels represent a reliable tool in diagnosing insulin resistance." (PMID 19291292, 2009). "The strong association between UA and GFR was not reduced (β = -0.48, P < 0.001) by further adjustments for inflammation (by including CRP) and insulin resistance (by including HOMA IR) to the previous model or repeat multivariable regression analysis with a stepwise and backward procedure." (PMID 19630964, 2009). "Insulin resistance and C-reactive protein (CRP) levels are strongly correlated in adults." (PMID 18570670, 2008). "SAD might however also reflect visceral fat better than other anthropometric measures which might be an explanation for the stronger correlation between SAD, CRP and insulin resistance." (PMID 17391519, 2007). "Anthropometric measurements (SAD, body mass index [BMI], waist circumference [WC] and waist-to-hip ratio [WHR]; all measured in supine position) and cardiovascular risk factors (C-reactive protein [CRP], insulin, glucose, insulin resistance [HOMA-IR], blood pressure and serum lipids) were assessed." (PMID 17391519, 2007). "The worsening of anthropometric and metabolic risk factors (such as homeostasis model assessment of insulin resistance (HOMA-IR), C-reactive protein (CRP), and lipid profile) may help explain how impaired glucose homeostasis contributes to the development of MASLD." (PMID 40299427, 2025). "Moreover, self-reported diagnosis cannot capture disease activity or severity and lacks the precision of quantitative biomarkers such as CRP levels or standardized indices of insulin resistance, which have been highlighted in prior studies as important for mechanistic interpretation." (PMID 41255642, 2025). "Furthermore, the chronic state of inflammation, characterized by increased levels of C-reactive protein, inflammatory cytokines, resistin, leptin, and adiponectin, affects insulin resistance, leading to the exhaustion of pancreatic beta cells and impairing the maintenance of normoglycemia." (PMID 40299945, 2025). "In addition, visceral fat accumulation was related to insulin resistance, glucose intolerance, elevated levels of C-reactive protein and tumor necrosis factor-α, all of which may further exacerbate CVDs." (PMID 40699163, 2025). "Both CRF and BMI-corrected HS during pregnancy were associated with lower hepatic insulin resistance (HOMA-IR), increased whole body insulin sensitivity (MATSUDA), and a lower risk of metabolic syndrome at 1-year postpartum, while HS alone was further related to lower CRP." (PMID 41276872, 2025).
Insulin resistance (continued). "Their findings indicated that admission CRP levels were positively associated with insulin resistance, independent of blood glucose levels, suggesting that inflammation may precede hyperglycemia in this context." (PMID 40725102, 2025). "Genes such as sirtuin-1 (SIRT1), C-reactive protein (CRP), C-X-C motif chemokine receptor 2 gene (CXCR2), as well as chemokines and interleukins such as interleukin 12 (IL12A) and C-X-C motif chemokine ligand 8 (CXCL8), are strongly associated with insulin resistance and T2D." (PMID 38674857, 2024). "Other factors such as lipids/cholesterol, insulin resistance, and fasting glucose levels may also lie within the causal pathway as they have also been shown to relate to CRP levels; however, data on these biomarkers were not available." (PMID 37388285, 2023). "In addition, the multivariate models of those studies may be a limitation, indeed covariates such as insulin resistance, renal function, CRP, abdominal circumference or other anthropometric indices alternative to BMI were not considered." (PMID 37217748, 2023). "As it predicted a reduced insulin secretion independent of insulin resistance, CRP might be associated with or lead to reduced islet beta-cell function in women after GDM." (PMID 37891561, 2023). "However, the association between inflammation (measured with CRP) and insulin resistance has not been evaluated in patients with CAP." (PMID 38202252, 2023). "A possible mechanism is that insulin resistance or elevated glucose is developed based on the increase in the cytokines; another possibility is that acute phase proteins such as CRP and alpha-a-acid glycoprotein induced by inflammatory response may lead to abnormal glucose metabolism in adipocytes." (PMID 36032093, 2022). "Both in vitro and in vivo studies have reported the regulation of PAI-1, SAA, and CRP expression to be closely influenced by the pro-inflammatory cytokines, TNF-α, IL-1β and IL-6, as well as hormones such as GCs which are also associated with insulin resistance and T2D." (PMID 35883605, 2022). "Notably, serum complement C3 was shown to have a stronger association with insulin resistance than highly sensitive C-reactive protein in non-diabetic Chinese patients." (PMID 35610262, 2022). "Although this analysis using structural equation modelling could not demonstrate this pathway via CRP, it could be that CRP lacks sensitivity as a marker of inflammation associated with insulin resistance and fatty liver." (PMID 35745097, 2022). "Collectively, CRP remains an important metabolic biomarker post-treatment, highly prone to worsening over time that should be closely monitored throughout survivorship, in addition to insulin resistance, especially among obese, insulin resistant breast cancer survivors." (PMID 35241143, 2022). "In addition, compared to subjects with an abundant microbiome, subjects with low richness in the gut microbiome had higher levels of C-reactive protein, leptin, dyslipidemia, insulin resistance, and inflammatory phenotypes, and gained more body weight and body fat." (PMID 36079841, 2022). "However, CRP concentrations between 2 and 10 μg/mL are considered to indicate metabolic inflammation, which could lead to the development of insulin resistance." (PMID 35883605, 2022). "We aimed to determine if visceral adiposes tissue (VAT) is associated with cardiometabolic risk factors (i.e., triglycerides, cholesterol, insulin resistance, C-reactive protein, and blood pressure), independent of BMI percentile, in a sample of primarily Hispanic adolescent girls." (PMID 36172390, 2022). "Finally, the IRAS, showed that high CRP baseline levels (>2.4 mg/L) amongst patients diagnosed with insulin resistance were associated with a higher risk of developing T2D and recognized a significant correlation between CRP and components of insulin resistance." (PMID 35883605, 2022).
Insulin resistance (continued). "Pro-inflammatory cytokines such as CRP, interleukin-6 (IL-6) and tumour necrosis factor alpha (TNF-α) are derived from immune cells or adipocytes and are implicated in inhibiting the insulin signalling cascade whilst also positively associated with insulin resistance." (PMID 36145067, 2022). "The main predicting factors of increased CRP are BMI and insulin resistance, but there is also a relationship between WBC count in PCOS and androgen concentration itself so that inflammation may be mediated not only through adiposity but also through increased androgen concentration." (PMID 32219132, 2020). "The main predicting factors of increased CRP are BMI and insulin resistance, but there is a relationship between WBC count in PCOS and androgen concentration itself so that inflammation may be mediated not only through adiposity but also through increased androgen concentration." (PMID 32219132, 2020). "In addition, increased levels of estrogen, progesterone, and adipocyte-derived hormones such as adiponectin, resistin, tumor necrosis factor alpha (TNFα), interleukin-6 (IL6), and C-reactive protein (CRP) are also suggested to play a role in the development of insulin resistance during pregnancy." (PMID 33114711, 2020). "Inverse associations were seen between a sphingomyelin composite score and C-reactive protein, a dihydroceramide composite score and diastolic blood pressure, and the final principal component that included glutathionone with fasting insulin and the homeostatic model of insulin resistance." (PMID 33079935, 2020). "At the end of each period, the components of the MS, insulin resistance, antioxidant capacity, and some oxidative (oxidized low-density lipoprotein [oxLDL]; thiobarbituric acid reactive substances) and inflammatory (high-sensitive C-reactive protein [hs-CRP]) markers were evaluated." (PMID 33269114, 2020). "In addition, several reports have indicated that high circulating concentrations of inflammatory mediators (including CRP, IL-6, TNF-α, and MCP-1) originate from obese adipose tissue and that the levels of these mediators are associated with the degree of insulin resistance." (PMID 31192262, 2019). "Moreover, a regression analysis revealed that body mass index, the homeostasis model assessment of insulin resistance and the high sensitivity C-reactive protein levels were confounding factors that affected the monocyte counts to high density lipoprotein cholesterol values." (PMID 29631598, 2018). "Serum concentrations of C-reactive protein (CRP, a highly specific systemic marker of inflammation) and TNF-α (a powerful pro-inflammatory cytokine) are both associated with an increased risk of developing insulin resistance, type 2 diabetes (T2D), cardiovascular disease (CVD) and cancer." (PMID 27410480, 2016). "Indeed, insulin resistance in RA patients was shown to be higher than that observed in patients with systemic lupus erythematosus, and was correlated with serum levels of IL-6, TNFα, and C-reactive protein (CRP)." (PMID 25988122, 2014). "The Atherosclerosis and Insulin Resistance (AIR) Study reported that ox-LDL levels were associated with both subclinical atherosclerosis, as assessed by ultrasonography, and inflammatory markers, including C-reactive protein (CRP) and tumor necrosis factor-α TNF-α." (PMID 24455214, 2013). "Insulin resistance leads to a perturbation in the lipid homeostasis, cytokines, and adipokines production, resulting in increased systemic inflammation, with higher levels of inflammatory markers such as C-reactive protein (CRP), interleukin (IL)-6, and tumor necrosis factor (TNF)-α." (PMID 23762872, 2013). "In addition, CRP was also correlated with fasting insulin and insulin resistance verified by HOMA." (PMID 21822486, 2012). "Furthermore, CRP is increased in maternal obesity, insulin resistance, and maternal dysglycemia." (PMID 22550485, 2012).